GSDMD (gasdermin D)
Diseases named in the same sentence as GSDMD in open-access papers (continued):
Sharing a sentence is not in itself a finding about the gene and the disease.
tumor (continued). "The expression of gasdermin D (GSDMD), accompanied by the upstream components of the NLRP3 inflammasome, is related to the activation of the inflammasome in the tumor." (PMID 36189269, 2022). "It is reported that the NLRP3/caspase-1/GSDMD-dependent pyroptosis is enhanced in NSCLC cells treated with polyphyllin VI, leading to the elimination of tumor cells." (PMID 35819638, 2022). "In the present study, by using bioinformatic databases, cell lines, and tumor samples, we investigated the correlation between NEK7 expression and GSDMD expression in human HCC." (PMID 35223495, 2022). "Encouraging antitumor efficacy has been achieved in multiple tumor models through the combination of VNP-mediated delivery and activation of GSDMD proteins and EI-NP-induced inhibition of ESCRT III-dependent membrane repair." (PMID 36280674, 2022). "In the present study, we examined a NEK7 expression pattern with GSDMD in l HCC and investigated the functional impact of NEK7-regulated pyroptosis on tumor progression." (PMID 35223495, 2022). "Together, these observations support the notion that GSDMD and GSDME act as tumor suppressors through programmed cell death and immune cell recruitment and propose them as prognostic markers for tumor progression and patient survival." (PMID 35844522, 2022). "MEG3 knockdown suppresses the activation effect of DDP on NLRP3/caspase-1/GSDMD pathway-mediated pyroptosis and alters the inhibitory effect of DDP on tumour proliferation and metastasis in triple-negative breast cancer." (PMID 35778526, 2022). "Depletion of GSDMD attenuates the proliferation of NSCLC cells and restricts the growth of tumor cells by facilitating caspase-3-induced apoptosis." (PMID 35819638, 2022). "GSDMD expression is negatively correlated with the mRNA levels of MLL3 and MLL4 in nearly all TCGA human tumor types, suggesting a general function of MLL3 and MLL4 in the control of GSDMD expression in human tumors." (PMID 36323669, 2022). "In the 27 PRGs, apart from CASP4, CHMP6, CHMP7, GSDMD, and TP63, the other 22 PRGs were expressed differentially at a significant level between primary tumor and paracancerous samples." (PMID 35938142, 2022). "Immunohistochemistry analysis of tumor xenograft samples suggested that in the radiation-treated group, circNEIL3 knockdown elevated the expression of γH2AX, AIM2, cleaved caspase-1, and GSDMD, but reduced the levels of PIF1 and BRCA1." (PMID 35190532, 2022). "In general, we found a higher expression of CanCord34 genes in the differentiated tumor cells, except for CCDC166, GSDMD, TSTA3, and highly purified BCSCs cells, compared to the other stem cell types." (PMID 36497066, 2022). "After the verification of the successful intracellular GSDMD protein delivery, next the efficacy of VNP-GD in triggering tumor cell pyroptosis was evaluated in both 4T1 and B16F10 tumor cells." (PMID 36280674, 2022). "Immunohistochemistry (IHC) was used to evaluate the differential expression of major PRGs (GSDMC, GSDMD, GSDME, NLRP3, NLRC4, IL1B) in selected tumor types (COAD, HNSC, KIRC, LIHC, LUAD, LUSC)." (PMID 36605187, 2022). "The killed tumor cells release factors such as ATP/HMGB, which are taken up by macrophages and induce intracellular macrophage caspase-1/gasdermin D activation, resulting in CRS." (PMID 36038533, 2022). "GSDMD modulated the EGFR/Akt signaling in NSCLC and promoted the proliferation of tumor by inhibiting apoptosis." (PMID 34298833, 2021). "GSDMA, GSDMC and PJVK are not detected in most human tissues (both tumor tissues and normal tissues), while GSDMB, GSDMD and GSDME are highly expressed in most human tissues (both tumor tissues and normal tissues), especially GSDMD." (PMID 34421915, 2021). "Taken together, these data suggested that DDP-induced pyroptosis suppressed tumor growth and metastasis via MEG3/NLRP3/caspase-1/GSDMD pathway in a xenograft animal model." (PMID 34326697, 2021).
tumor (continued). "Of the five GSDM gene members, only GSDMD expression showed a positive correlation with CD8+ T cell marker genes (e.g., CD8A, CD8B, PRF1, GZMA, GZMB, and IFNG) in CTLs across all three tumor cohorts." (PMID 34429144, 2021). "A positive correlation between GSDMD and CD8A, GZMB, and IFNG expression in CTLs was also seen in many other tumor types and in 30 primary tumor samples from patients with NSCLC, further confirming the associations seen from TCGA." (PMID 34429144, 2021). "In total, 5 of the 34 pyroptosis-related genes were related to prognosis and four of them (ELANE, GPX4, GSDMD, and TIRAP) had different expression values between tumor and normal tissues, which were, thus, chosen as prognostic DEPRGs." (PMID 34722500, 2021). "Decreased GSDMD is observed in CRC tissues, with levels negatively correlating with tumor dissemination, tumor aggressiveness, and survival rates after 5 years." (PMID 35111698, 2021). "Studies had showed that GSDMD and GSDME-mediated canonical inflammasome signaling and pyroptosis play vital roles in the immune response of cancer tissues through modulating the tumor immune microenvironment." (PMID 34421915, 2021). "Knockdown of MEG3 abolished the activation effect of DDP on NLRP3/caspase-1/GSDMD pathway-mediated pyroptosis, and reversed the suppression of DDP on tumor growth and metastasis ability in vitro and in vivo." (PMID 34326697, 2021). "Tumor tissue sections in the HRW group presented much higher NLRP3, caspase-1 and GSDMD staining by IHC." (PMID 31924176, 2020). "In general, GSDMA, GSDMC, GSDMD, and GSDME are known as tumor suppressors, and GSDMB was shown to function as an oncogene." (PMID 33348858, 2020). "Tumor tissue sections in the HRW groups presented moderate-to-strong positive expression of NLRP3, caspase-1 and GSDMD." (PMID 31924176, 2020). "Though tumor tissue sections in the HRW and NC groups presented moderate-to-strong positive expression of NLRP3, caspase-1 and GSDMD, the HRW group showed much higher staining by IHC." (PMID 31924176, 2020). "Moreover, specific depletion of GSDMD in hematopoietic cells also suppressed the dysfunction of T cells and NK cells in the MC38 tumor model." (PMID 40759573, 2025). "We believe this study identifies a new nonpyroptotic role of GSDMD in tumor immunity, proposing GSDMD as a potential target for cancer immunotherapy." (PMID 40759573, 2025). "GSDMD is extensively expressed in both non-tumor and tumor diseases, and its inhibition has shown considerable potential in alleviating disease pathology, positioning it as a promising therapeutic target." (PMID 39994107, 2025). "ICAM1 antibody‐bound ICG triggers tumor‐specific, caspase‐1‐independent pyroptosis via CTSS‐mediated GSDMD cleavage, activates antitumor immunity, and synergizes with anti–PD‐1 therapy, offering a non‐apoptotic strategy to overcome resistance in cancer treatment." (PMID 40539828, 2025). "To test this, we first confirmed that GSDMD deficiency in T cells, and its inactivation by DSF treatment, both decreased the IL-2 levels in the TME of multiple tumor models, regardless of the presence or absence of CD8+ T cells." (PMID 40759573, 2025). "In line with the myeloid depletion results and a recent report, specific deletion of GSDMD in myeloid cells had no impact on tumor growth." (PMID 40759573, 2025). "This study reveals that YY2 high expression‐mediated chromosome missegregation/micronuclei formation triggers pyroptosis and CTL activation by activating AIM2/caspase‐1/GSDMD cytosolic dsDNA response, and YY2/anti‐PD‐L1 combinatorial anti‐tumor therapeutic strategy." (PMID 39903759, 2025). "In addition, another GSDMD inhibitor, dimethyl fumarate (DMF), also promoted MC38 tumor growth in WT mice." (PMID 40759573, 2025). "We investigated the differential expression of GSDMD in tumor tissues compared to adjacent non-cancerous tissues across 15 tumor types." (PMID 40491921, 2025).
tumor (continued). "We designed wild‐type GSDMD (wt), GSDMD cleavage site mutant (mut), GSDMD‐C‐terminal (C), N‐terminal with membrane‐binding domain mutant (MCD), and N‐terminal cytotoxic domain (CD) plasmids to determine which domain of GSDMD regulates MMP14 expression and tumor metastasis in OSCC." (PMID 40178046, 2025). "Gasdermin D (GSDMD) is the main executioner of pyroptosis, and is considered as a tumor suppressor." (PMID 38678251, 2024). "There was a significant negative correlation between miR-221-5p and GSDMD expression in tumor tissues (P < 0.05)." (PMID 39439418, 2024). "For instance, GSDMD overexpression was shown to enhance eIF2α phosphorylation and activate endoplasmic reticulum (ER) stress response to promote tumor cell apoptosis, rather than pyroptosis, during cisplatin chemotherapy." (PMID 39253076, 2024). "In the NT GSDMD-treated group we achieved prolonged survival compared to the empty vector-treated mice, yet tumor growth did not cease, whereas NT GSDMD + IL-1β therapy resulted in tumor suppression and survival of 17% of treated mice." (PMID 39737979, 2024). "Based on our observations, we speculate that IL-1β, following inflammasome activation and GSDMD pore formation, attracts myeloid cells to the tumor and promotes CRC development by signaling to cancer cells, myeloid cells, as well as tumor-infiltrating T cells." (PMID 38898209, 2024). "There was hyperactivation of GSDMD, GSDME, and p-MLKL in dMMR tumor cells." (PMID 38740747, 2024). "It is therefore possible that under certain conditions, the absence of GSDMD only results in improved anti-tumor immunity in combination with immunotherapy." (PMID 39224600, 2024). "NT GSDMD therapy not only increased the survival time but also led to full remission in approximately 20% of treated animals and an extension of tumor-free survival with no recurrence to 500 days when mice were eliminated due to old age." (PMID 39737979, 2024). "Knockdown of MEG3 could reverse the inhibition of cisplatin on tumor growth and metastasis thorough NLRP3/caspase‐1/GSDMD pathway‐mediated pyroptosis." (PMID 36237132, 2023). "designed the novel pyroptosis inducer, Cu-TBB, which can specifically target the tumor cells and promote tumor cell pyroptotic death via the caspase-1/GSDMD pathway without damaging normal human cells and organs." (PMID 38016064, 2023). "IL-18 and GSDMD, both constituents of the canonical pathway of pyroptosis, were also upregulated in the tumor samples that were assessed, further proving the activation stage of pyroptosis in BC." (PMID 37511974, 2023). "Nig could activate NLRP3 inflammasome and caspase‐1 protein to cleave GSDMD regulated by DAC, which could trigger murine 4T1 tumor cell pyroptosis for systemic anticancer immunity." (PMID 37125240, 2023). "Gasdermin D (GSDMD) was found to be up-regulated in NSCLC and promote tumor growth." (PMID 36941988, 2023). "Mechanistically, NMs trigger the classical caspase-1-mediated pathway of pyroptosis in non-tumor cells, predominantly involving the GSDMD molecule, although some studies have not assessed the expression of GSDM proteins." (PMID 38264354, 2023). "Taken together, we concluded that non-canonical inflammasome activation leads to GSDMD-mediated pyroptosis in these tumor cell lines." (PMID 35022507, 2022). "Collectively, it was demonstrated here that VNP-GD could efficiently trigger tumor cell pyroptosis by the combination of enhancing intracellular delivery of GSDMD via VNP and further activation of N-terminal GSDMD mediated by VNP-induced caspase 1 cleavage." (PMID 36280674, 2022). "Furthermore, not all the transcripts associated with the inflammasome complex were enriched in the tumor, such as IL18, AIM2, PYCARD, and GSDMD." (PMID 36439171, 2022). "Ectopic expression of wild-type but not D276A mutant GSDMD into B16 cells greatly suppresses tumor growth and thus reduces the tumor burden in C57BL/6J mice." (PMID 36323669, 2022).
tumor (continued). "In conclusion, GSDMD, GSDMB, and AIM2 are all promising new targets in cancer therapy, which may be involved in the death mechanism of tumor cell therapy through pyroptosis." (PMID 36569221, 2022). "Among these DEGs, CDKN2A, GNG7, GSDMD, and POLG are known tumor suppressors in GC." (PMID 36230863, 2022). "In addition, NSCLC patients with larger tumor size and more advanced tumor lymph node metastasis (TNM) stage occurred in patients with GSDMD overexpression." (PMID 36523974, 2022). "Gasdermin D (GSDMD) is a 487 amino acid cytoplasmic protein with roles in epithelial differentiation and tumor suppression, and may also be involved in myocardial I/R injury via its activation by inflammasome to cause pyroptosis." (PMID 35422485, 2022). "However, nuclear GSDMD was negatively related to CD68+ macrophages in the tumor invasive front and CD8+ lymphocytes in the tumor center." (PMID 35739593, 2022). "Therefore, to achieve selective protein release inside tumor cells, we first synthesized a GSH responsive linker to crosslink GSDMD proteins to form protein cages (designated GD) that can be easily modified on the surface of VNP." (PMID 36280674, 2022). "To explore the role of GSDMD in vivo, we next constructed a nude mouse xenograft tumour model using GSDMD-overexpressing and negative conrol cells, respectively." (PMID 35289335, 2022). "In the course of cisplatin chemotherapy, GSDMD induces cell apoptosis by promoting eIF2α phosphorylation to activate ER stress and increases the sensitivity of tumours to cisplatin in a nonpyrolytic manner." (PMID 35289335, 2022). "Activated GSDMD/GSDME protein leads to the formation of membrane pores and mediates the maturation and release of IL-1β and IL-18, which subsequently induces strong inflammatory response in tumor microenvironment." (PMID 34830775, 2021). "To determine whether DDP-induced pyroptosis suppresses tumor growth and metastasis via MEG3/NLRP3/caspase-1/GSDMD pathway in vivo, we established a xenograft model of nude mice bearing the MDA-MB-231 cells." (PMID 34326697, 2021). "Additionally, the immunohistochemistry assay identified the upregulation of caspase-4, GSDMD, and phospho-RIPK3 expression in xenograft tumor tissues following NO.0449-0145 treatment." (PMID 34006852, 2021). "Activated caspase-1 and caspase-11/4/5 cleave gasdermin D (GSDMD) in inflammatory cells, while caspase-3 cleaves gasdermin E (GSDME) in tumor cells, to release the N terminal domain of gasdermins that inserts into the plasma membrane to form pores that allow intracellular molecules to pass through." (PMID 33430381, 2021). "Moreover, other studies showed that GSDMD/GSDME mRNA methylation induces decreased GSDMD/GSDME expression levels in tumor cells when compared with normal cells, making it difficult to activate pyroptosis in tumor cells." (PMID 33840390, 2021). "GSDMD-silenced NSCLC cells show decreased epidermal growth factor receptor signaling, increased caspase 3 decomposition and enhanced apoptosis, resulting in the suppression of tumor growth in transplanted mice." (PMID 31501419, 2019). "Moreover, co-culture experiments involving isolated NK cells and tumor cells revealed that SNRPE targeting heightened the cytotoxicity of NK cells, while GSDMD knockdown disrupted the SNRPE silencing-induced augmentation of antitumor immunity and inhibition of tumor growth (Figure 6CDEF)." (PMID 40386046, 2025). "Moreover, pH‐responsive nanoparticles (NPs) for the systemic delivery of a GSDMD siRNA (siGSDMD) is developed and showed that this NP‐delivered siGSDMD can effectively inhibit OSCC tumor growth and metastasis via the efficient silencing of GSDMD expression in vivo." (PMID 40178046, 2025). "It is possible that the limited IL-2 production by intratumoral CD4+ T cells could be in part due to GSDMD inactivation, since a portion of CD4+ T cells did not display GSDMD activation in tumor sections." (PMID 40759573, 2025).
tumor (continued). "Ablation of GSDMD in our mouse model of sporadic CRC resulted in reduced tumor numbers, but not tumor size, suggesting that GSDMD may mainly promote the early phases of CRC, i.e., tumor initiation/promotion, but not tumor growth." (PMID 38898209, 2024). "We show that NT GSDMD electroporation does not lead to a decrease in tumor growth, not even when pyroptosis was enriched with IL-1β pretreatment and all animals were rapidly eliminated demonstrating that the protective effects of pyroptosis and cytokine-armed pyroptosis depend on the immune system." (PMID 39737979, 2024). "Cell function experiments and nude mouse tumor transplantation assays confirmed that LINC00365 could regulate the expressions of pyroptosis-related proteins such as Caspase-1, Caspase-11, NLRP3 and GSDMD." (PMID 39439418, 2024). "Activating GSDMD‐ or GSDME‐driven pyroptosis may become a promising therapeutic approach in various cancers, offering the potential to bypass some of the drug resistance mechanisms often observed in tumour cells." (PMID 38804602, 2024). "Unlike GSDMD, several studies have implicated GSDME as a tumor suppressor." (PMID 37077542, 2023). "Besides GSDMD, GSDME also plays different roles in tumor development." (PMID 37313458, 2023). "A lack of GSDMD hampered the ability of CD8+ T cells to destroy tumor cells." (PMID 36707884, 2023). "Interestingly, PRGs with CNV gain, including GSDMD, GSDMC, CHMP4C and CHMP6, were significantly higher in HCC samples than in adjacent non-tumor samples (p < 0.001), suggesting that CNVs may regulate PRGs expression." (PMID 36650832, 2023). "In addition, caspase-8 in tumor cells can be activated by TNF-α to cleave GSDMC, while in murine macrophage, activation of caspase-8 in the context of TAK1 inhibition results in cleavage of both GSDMD and GSDME." (PMID 36823153, 2023). "Our findings support a general function of tumor-cell pyroptosis in promoting anti-tumor immunity and reveal the functional link between regulation of MLL4-dependent enhancers and transcriptional induction of interferon signaling and GSDMD-mediated pyroptosis in tumor cells for immunomodulation." (PMID 36323669, 2022). "4T1 tumor cells without any treatment showed negligible GSDMD protein expression, while VNP-GD could efficiently deliver GSDMD to the cytoplasm of 4T1 cells." (PMID 36280674, 2022). "GSDMD was also proved to mediate pyroptosis and effectively stimulate tumor immunogenicity, promoting the maturation of dendritic cells (DC) cells and fully activating T cells reliant adaptive immune responses in TNBC, ultimately eradicating distant cancers while killing the original tumor." (PMID 36119049, 2022). "In addition, the high level of GSDMD do not induce pyroptosis but is associated with aggressive characteristics, such as more advanced tumor-lymph node metastasis (TNM) phase, larger tumor size, and poorer prognosis in NSCLC." (PMID 36467499, 2022). "Moreover, the expression of caspase-1, IL-1β, and GSDMD was negative correlation with increasing tumor grade, clinical stage, and poor clinical prognosis in BC, indicating pyroptosis played a central role in BC tumorigenesis and progression." (PMID 35464869, 2022). "Moreover, the addition of EI-NP enhanced the pyroptosis as evidenced by the increased generation of tumor antigen HMGB1 but did not alter the expression of cleaved caspase 1 or cleaved GSDMD." (PMID 36280674, 2022). "Recently, it has been reported that two members of the GSDM family, namely GSDMD and GSDME, stimulate numerous downstream pyroptotic pathways, and the downregulation of these molecules conversely contributed to tumorigenesis and proliferation in the tumor cell microenvironment." (PMID 36003332, 2022).